FASN (fatty acid synthase)
Diseases named in the same sentence as FASN in open-access papers (continued):
Sharing a sentence is not in itself a finding about the gene and the disease.
ovarian carcinoma (continued). "As an example of FASN promoting cancer metastasis, FASN expression enhanced peritoneal metastasis of ovarian cancer in part through the induction of epithelial mesenchymal transition (EMT)." (PMID 33401771, 2021). "In summary, miR-33b acts as a tumor suppressor, inhibiting oncogenesis and targeting ovarian cancer lipid metabolism by downregulating TAK1/FASN/CPT1A/NF-κB signaling." (PMID 34638280, 2021). "In ovarian cancer, the expression of fatty acids synthase (FASN), the key enzyme of de novo lipogenesis, was found increased." (PMID 33732237, 2021). "DC fail to present antigens and primary T cell is disability when they are cultured in the ascites of ovarian cancer patients with activated FASN, which further support this view." (PMID 33117713, 2020). "FASN has been shown to induce epithelial-mesenchymal transitions, thereby increasing the chances of ovarian cancer metastasis to the peritoneal cavity." (PMID 32698888, 2020). "There is a relationship between the stage of ovarian cancer and FASN levels; in one study, the level of FASN in end-stage cancer patients was 94.1%, while in patients with stage I ovarian cancer, it was 12.5%." (PMID 32698888, 2020). "To address this, we exposed clear cell (SKOV3) and serous (OVCAR3) ovarian cancer cells, two major histological subtypes of OC, to the FASN selective inhibitor G28UCM6,7." (PMID 32913236, 2020). "In one study, immunohistochemical examination found no FASN expression in normal ovarian cells, but excessive expression of FASN was found in ovarian cancer, especially in the advanced stages." (PMID 33112541, 2020). "In short, ovarian cancer endogenous FASN can induce tumor cells’ immune escape through lipid accumulation in TIDC and subsequent T cell rejection and dysfunction." (PMID 33117713, 2020). "High FASN expression was demonstrated in as many as 94.1% of patients with FIGO stage IV ovarian cancer but in only 1.25% of patients with stage I ovarian cancer." (PMID 33112541, 2020). "Mechanistic studies have found that FASN activation in ovarian cancer cells can induce the resulting lipid accumulation at high concentrations in the tumor microenvironment." (PMID 33194756, 2020). "The clinical data showed that, in the advanced stage of ovarian cancer, the abnormally increased expression of FASN was positively correlated with the state of immunosuppression." (PMID 33194756, 2020). "It was one of the first FASN inhibitors that showed anti-cancer effects in breast and ovarian cancer both in vitro and in vivo." (PMID 32872164, 2020). "The combined treatment of low toxic AMPK activators, the transforming growth factor beta-activated kinase 1 (TAK1) and fatty acid synthase (FASN) inhibitors synergistically impair oncogenic augmentation of ovarian cancer." (PMID 31372520, 2019). "In this study, ovarian cancer cells utilize lipid metabolism in the ascites or omental microenvironment during metastatic progression through AMPK/ACC/FASN-mediated lipogenesis and AMPK/TAK1/NF-κB signaling cascades." (PMID 31372520, 2019). "Consistently, the depletion of FASN also led to remarkable reduction of lipid droplet formation in ovarian cancer cells, supporting the important role of FASN in lipogenesis of ovarian cancer cells." (PMID 31372520, 2019). "As expected, compared to FASNlow OvCa bearing mice, there were significantly higher concentrations of unsaturated fatty acids, saturated fatty acids, and triacylglycerols in ascites of ID8 ovarian cancer-bearing mice with higher FASN expression." (PMID 30619288, 2018). "In our study, we have explored the use of the FASN inhibitor orlistat as a way of overcoming resistance to cisplatin in cisplatin‐refractory ovarian cancer and examined their effects as monotherapies or as a combination, on tumour metabolism." (PMID 29569717, 2018). "In sum, these data indicated an inverse correlation between ovarian cancer-intrinsic FASN level and tumor infiltration by CD8+ CTLs in human ovarian cancer." (PMID 30619288, 2018).
ovarian carcinoma (continued). "Mechanistically, FASN activation in ovarian cancer cell-induced the resulting increase of lipids present at high concentrations in the tumor microenvironment." (PMID 30619288, 2018). "Using Meyniel's dataset, we showed that the mRNA level of FASN was significantly increased in higher grade patients with ovarian cancer." (PMID 30619288, 2018). "Here, our data showed that constitutive activation of FASN in ovarian cancer cell lead to abnormal lipid accumulation and subsequent inhibition of tumor-infiltrating DCs (TIDCs) capacity to support anti-tumor T cells." (PMID 30619288, 2018). "Consistent with our previous study, FASN was one of the top increased genes in human ovarian cancer." (PMID 30619288, 2018). "Anyway, FASN downregulation has also been reported elsewhere, by C75 in A2780 ovarian cancer cells in a dose-dependent manner, and by EGCG, in A549 lung cancer cells and in chemo-sensitive and -resistant MDA-MB-231 and HCC1806 TNBC cells." (PMID 29751678, 2018). "To explore the effect of FASN upregulation on tumor microenvironment (TME), we analyzed the expression of FASN in human ovarian cancer tissues by immunohistochemistry (IHC)." (PMID 30619288, 2018). "In this study, we depicted that elevated FASN expression presented in ovarian cancer with more advanced clinical phenotype and correlated with the immunosuppressive status, which characterized by the lower number and dysfunction of infiltrating T cells." (PMID 30619288, 2018). "Elevated FASN levels have been identified in breast, prostate, colon, and ovarian cancer patients blood in comparison with normal subjects using ELISA." (PMID 26621841, 2016). "The present study focuses on the correlation between ovarian cancer and expressions of FASN and HER2." (PMID 25433947, 2015). "FASN also was highly overexpressed at both mRNA and protein levels in primary culture of high-grade ovarian carcinoma cells, although to a lesser extent than in ovarian cancer cell lines." (PMID 25947066, 2015). "Preclinical reversal of chemoresistance by FASN inhibition was described before in ovarian cancer and other human malignancies." (PMID 25947066, 2015). "Incubation with 35 μmol/L of either FASN inhibitor alone for 72 h substantially inhibited cell viability in all studied ovarian cancer cell lines." (PMID 25947066, 2015). "Third, single-agent administration of a FASN inhibitor, C93, blocked growth of carboplatin-resistant, and, especially, paclitaxel-resistant ovarian cancer cell lines." (PMID 25947066, 2015). "It clusters together genes with common expression profiles and confirms that the expression of SREBF1, SCD1 and FASN is coordinately up-regulated in ovarian cancers." (PMID 26807200, 2015). "Patients with FASN overexpression in ovarian cancer tend to have a worse overall survival rate (p = 0.000)." (PMID 25433947, 2015). "The pharmacological inhibition of FASN with C93, a synthetic FASN inhibitor, causes rapid energy depletion and activation of AMPK, which leads to cytotoxicity, in ovarian cancer cells." (PMID 25970773, 2015). "In ovarian cancer cell lines and primary cultures cerulenin, decreased FASN protein expression, de novo fatty acid synthesis, cell growth, and cell viability much more effectively than did C75." (PMID 25947066, 2015). "We investigated FASN overexpression as a therapeutic and chemosensitization target in ovarian cancer tissue, cell lines, and primary cell cultures." (PMID 25947066, 2015). "In the study, we found that FASN has abnormally high expression in ovarian cancer, which was consistent with previous report." (PMID 25433947, 2015). "Correspondingly, FASN knockdown using RNA interference in ovarian cancer cells inhibits the migration in vitro and experimental peritoneal dissemination in vivo." (PMID 24979135, 2014). "In this study, we demonstrate that elevated FASN expression promotes the malignant properties of ovarian cancer cells in vitro." (PMID 24979135, 2014).
ovarian carcinoma (continued). "In this study, we evaluated FASN expression in ovarian cancer and investigated how FASN regulates the aggressiveness of ovarian cancer cells." (PMID 24979135, 2014). "Knockdown FASN by siRNA significantly suppresses experimental peritoneal metastasis of ovarian cancer." (PMID 24979135, 2014). "To study the role of FASN in the metastases of human ovarian cancer, we investigated the expression of FASN in human ovarian cancer tissue samples, as well as the function of FASN in human ovarian cancer cell lines." (PMID 24979135, 2014). "Taken together, our work demonstrates that FASN promotes the peritoneal dissemination of ovarian cancer cells, at least in part through the induction of EMT." (PMID 24979135, 2014). "In summary, the authors have provided evidence that higher FASN expression is related to the aggressiveness and peritoneal metastasis of ovarian cancer cells." (PMID 24979135, 2014). "DAPs effectively inhibit ovarian cancer cell migration and invasion by altering the FASN and FAK expression." (PMID 23663277, 2013). "FASN is an enzyme responsible for de novo synthesis of lipids from sugars, is overexpressed in 80% of ovarian carcinomas, and has been shown to be a predictor of poor survival." (PMID 23591839, 2013). "DAP-F(p)-NOH targets FASN, resulting in inhibition of migration and invasion in ovarian cancer cell lines." (PMID 23663277, 2013). "FASN is overexpressed in ovarian cancer, and overexpression has been related with aggressive biologic behavior, suggesting a functional role for fatty acid synthesis in the growth, survival, and expansion/proliferation of cancer cells." (PMID 23663277, 2013). "Recent evidence shows that FASN inhibition induces apoptosis, via inactivation of pAKT and dephosphorylation of Bad in human cancer cells, including ovarian cancer cells." (PMID 23663277, 2013). "Genome-wide mRNA analysis of the naïve and MT19c treated xenograft tumors clearly identified MT19c action on FASN expression in MT19c treated ovarian cancer xenograft (p = 0.00000000055)." (PMID 22509304, 2012). "Numerous studies have shown overexpression of FASN in human epithelial ovarian cancer (EOC) and cancers of breast, prostate, colon, lung, endometrium and papillary thyroid." (PMID 22509304, 2012). "Although previous reports have shown the role of FASN expression in ovarian cancer, the current study provides new findings that should have several biological and clinical implications." (PMID 20508725, 2010). "All benign cystadenomas and normal ovarian surface epithelium (n = 35) display undetectable to very low FASN staining (mean score = 0) whereas ovarian carcinomas of various histologic subtypes show FASN immunoreactivity (mean score ≥ 1) in most cases." (PMID 20508725, 2010). "The dependence of drug resistant tumor cells on FASN suggests a potential application of FASN-based therapeutics for recurrent ovarian cancer patients." (PMID 20508725, 2010). "Fatty acid synthase (FASN) is overexpressed in ovarian cancer and promotes tumor growth." (PMID 40395324, 2025). "Similarly, ovarian cancer progression relies on fatty acid metabolism, and FASN upregulation in ovarian tumors correlates to shorter overall survival." (PMID 38112643, 2024). "Similarly, praeruptorin B (20, 40, 60 μmol/L) was reported to inhibit both the proliferation and migration of SK-OV-3 ovarian cancer cells, as well as downregulate the expression of FASN, c-Myc, SREBP-1c, and cyclin D1." (PMID 38633612, 2024). "Interestingly, FASN overexpression has been also correlated with an immunosuppressive status in ovarian cancer, with a lower number and dysfunctional infiltrating T cells within the tumor." (PMID 38425123, 2024). "FASN plays a critical role in the peritoneal metastasis of ovarian cancer." (PMID 38003694, 2023). "Lipid-rich microenvironment may cause epigenetic silencing miR-33b, which negatively modulates ovarian cancer peritoneal metastases by suppressing TAK1/FASN/CPT1A/NF-κB signaling." (PMID 38003694, 2023).
ovarian carcinoma (continued). "In addition, FASN is recognized as a therapeutic and chemosensitization target in ovarian cancer tissue, cell lines, and primary cell cultures." (PMID 38003694, 2023). "Third, PPIs could potentially inhibit fatty acid synthase (FASN) using the crystal structure of FASN thioesterase, inducing apoptosis in chemosensitive and platinum-resistant ovarian cancer cells." (PMID 36551573, 2022). "Moreover, inhibiting FASN using cerulenin-sensitised cisplatin-resistant ovarian cancer cell lines to cisplatin implicates FASN in promoting chemoresistance in gynaecological cancers." (PMID 35448537, 2022). "For instance the over-expression of Fatty Acid Synthase (FASN) which is a key lipogenic enzyme has been reported to be associated with proliferation, chemoresistance and poor prognosis of ovarian cancer and FASN inhibitors have been shown to promote cancer cell apoptosis." (PMID 36381193, 2022). "Thus, some studies have suggested using FASN as a metabolic marker for ovarian cancer cell proliferation." (PMID 36230617, 2022). "For instance, FASN expression facilitated peritoneal metastasis by mediating EMT in ovarian cancer." (PMID 35047398, 2021). "Moreover, combination treatment of C75 (FASN inhibitor) and cisplatin resulted in greater growth inhibition of ovarian cancer in vivo than cisplatin treatment alone." (PMID 34298999, 2021). "We next investigated whether depletion of TAK1 suppresses fatty acid biosynthesis and ATP production in OCM-cocultured ovarian cancer cells by targeting FASN and CPT1A." (PMID 34638280, 2021). "To determine whether the effectors of the COL11A1 signaling, Src, Akt, and AMPK, also play a role in upregulating FASN in ovarian cancer cells, we blocked these signaling molecules using pharmacological inhibitors and measured the expression of FASN." (PMID 32312965, 2020). "Because the majority of cancers rely on the FASN-mediated de novo fatty acid synthesis pathway, FASN could be an attractive therapeutic target, and inhibition of FASN has shown antitumor effects in ovarian cancer." (PMID 33194756, 2020). "Cerulenin treatment of mice carrying ovarian cancer OVCAR-3 xenografts shows a promising anticancer effect where tumor FASN activity is greatly reduced and is accompanied by regression of established ascites tumors with significant improvement in mice survival at end-point." (PMID 32872164, 2020). "FASN is overexpressed in a wide variety of malignancies including ovarian cancer (OC)." (PMID 32913236, 2020). "They show that combined treatment of AMPK activators and TAK1/FASN inhibitors could impair ovarian cancer peritoneal metastasis." (PMID 31372520, 2019). "To specifically assess the effect of ovarian cell-intrinsic FASN activity in regulating the immune response, we first explore the link between ovarian cancer-intrinsic FASN expression and the accumulation of lipids in the tumor microenvironment of ovarian cancer." (PMID 30619288, 2018). "Therefore, our data provide a mechanism by which ovarian cancer-intrinsic FASN oncogenic pathway induce the impaired anti-tumor immune response through lipid accumulation in TIDCs and subsequently T-cells exclusion and dysfunction." (PMID 30619288, 2018). "Likewise, the FASN inhibitor C75 has significant antitumor effects on BC cells as well as prostate and ovarian cancer cells." (PMID 30250408, 2018). "As such, FASN has been shown to be important in several cancer types, including ovarian cancer." (PMID 30619288, 2018). "Here we conclude that ovarian cancer cell-intrinsic activation of an oncogenic FASN pathway can result in the exclusion of the host immune response, including the dysfunction of dendritic cells and the absence of a T-cell infiltrate within the tumor microenvironment." (PMID 30619288, 2018).
ovarian carcinoma (continued). "In our study, we investigated whether FASN inhibition using orlistat is an effective adjunctive treatment for ovarian cancers that have become platinum resistant using a cisplatin‐resistant ovarian tumour xenograft model in mice." (PMID 29569717, 2018). "Notably, in a mouse model, we showed that tumor cell-intrinsic FASN drove ovarian cancer (OvCa) progression by blunting anti-tumor immunity." (PMID 30619288, 2018). "Adhesion and invasion are early steps involved in the metastatic process for ovarian cancer, which has a complex molecular basis that involves adhesion molecules, cell surface receptors, oncogenes, chloride channels, fatty acid synthase, and focal adhesion kinase." (PMID 26503475, 2016). "Towards this direction, it was demonstrated that targeting SCD1 for inhibition increases apoptosis of renal carcinoma cells in vitro and in vivo and lung cancer cells in vivo, while in ovarian cancer, FASN inhibitors induce cell cycle blockage and stimulate apoptosis." (PMID 26807200, 2015). "However, unlike other investigators, we detected a reducing effect of cerulenin on FASN protein expression and cell viability considerably exceeding that of C75 in ovarian cancer cell lines when the drugs were given as single agents." (PMID 25947066, 2015). "FASN inhibition induced apoptosis in chemosensitive and platinum-resistant ovarian cancer cells and may reverse cisplatin resistance." (PMID 25947066, 2015). "A significantly increase in FASN expression in high stage of ovarian cancer was presented, which could be due to the fact that overexpression of FASN can provide material and energy for the rapid proliferation of tumor." (PMID 25433947, 2015). "Therefore, we conducted the present study to confirm FASN overexpression and to investigate the effects of two specific FASN inhibitors in ovarian cancer cells, including platinum-resistant cells." (PMID 25947066, 2015). "However, the attenuation of downstream regulators of FASN, as expected from treatment with C75 in the responsive A2780 ovarian cancer cell line, was just partially observed in simvastatin-treated cell lines." (PMID 25978957, 2015). "Three main factors provide rationale for investigating FASN overexpression in ovarian carcinoma." (PMID 25947066, 2015). "First, we confirmed and extended our earlier observations and others of considerable FASN overexpression in human ovarian cancer cells relative to that in healthy human tissue with a tendency towards higher expression in more aggressive, de-differentiated tumors." (PMID 25947066, 2015). "It is reported that a cross talk between ErbB and FASN mediates ovarian cancer cells proliferation." (PMID 25433947, 2015). "We speculated that whether an ErbB/FASN cross talk plays a vital role in mediating malignant phenotype of ovarian cancer." (PMID 25433947, 2015). "Some literature for ovarian cancer suggested that FASN could regulate the expression of HER2 through PI3k-Akt pathway." (PMID 25433947, 2015). "We thus hypothesized that specific FASN inhibition could exert therapeutic effects in highly FASN-expressing ovarian cancer cells, including re-inducing chemosensitivity in platinum-resistant cells." (PMID 25947066, 2015). "Overexpression of FASN in human epithelial ovarian cancer (EOC) has been shown." (PMID 22509304, 2012). "Finally, C93, a new FASN inhibitor, induced massive apoptosis in carboplatin/paclitaxel resistant ovarian cancer cells." (PMID 20508725, 2010). "Interestingly, Ets-1 was also found to be involved in the regulation of increased FASN gene expression in our ovarian cancer model." (PMID 21042593, 2010).